NF1 (neurofibromin 1)
Diseases named in the same sentence as NF1 in open-access papers (continued):
Sharing a sentence is not in itself a finding about the gene and the disease.
neurofibroma (continued). "To investigate whether the Nf1Arg681* and the Nf14F allele can induce neurofibroma development in vivo, we generated two conditional knockout NF1 mouse models employing a DhhCre transgenic mouse line." (PMID 27482814, 2016). "In summary, we have engineered and characterized the first NF1 patient-based germ line NF1 mutations modeled in mice, establishing that the Nf1Arg681* allele profoundly reduces neurofibromin expression and leads to plexiform neurofibroma formation." (PMID 27482814, 2016). "Zebrafish models of MMR deficiency also feature neurofibromas and other NF1-associated tumors." (PMID 25329635, 2014). "Additionally, a Sleeping Beauty forward genetic screen demonstrated that while benign neurofibromas had insertions in either Nf1 or Pten, these mutations only co-occurred in MPNSTs." (PMID 24681606, 2014). "Finally it would be very interesting to look into what happens to both wildtype NF1 allele and the NF1 duplicated segment in the malignant tissue, such as lymphoma specimens and in the apparent neurofibromas." (PMID 25580325, 2014). "In presence of a NF1 gene mutation, neurofibroma should also be considered." (PMID 24708790, 2014). "Immunohistochemical analysis and real-time quantitative reverse transcription polymerase chain reaction showed increased expression of EMT-related transcription factors including Snail, Slug, Twist, ZEB1 and ZEB2 in NF1-associated neurofibroma specimens and NF1-derived Schwann cells." (PMID 25026295, 2014). "This may be because patients with NF1 have a somatic mutation in the NF1 tumor suppressor gene, which results in the development of benign nerve sheath tumors called plexiform neurofibromas, which are at risk for malignant degeneration." (PMID 25452937, 2014). "The majority of NF1-associated MPNSTs arise from preexisting plexiform neurofibromas." (PMID 25452937, 2014). "Consistent with Knudson’s two-hit hypothesis, NF1 patients with a heterozygous germline NF1 mutation develop a somatic mutation in the second wild-type NF1 allele, resulting in the development of neurofibromas." (PMID 24137429, 2013). "The issue of possible gender predilection for FMGCs to appear in NF1-associated neurofibromas remains unclear as well." (PMID 23890233, 2013). "Consistent with Knudson's two-hit hypothesis, NF1 patients harbouring a heterozygous germline NF1 mutation develop neurofibromas upon somatic mutation of the second wild-type NF1 allele." (PMID 23947441, 2013). "Importantly, the human-zebrafish copy number loss intersections included all 3 genes whose hereditary mutation is known to predispose individuals to Schwann cell tumors (neurofibromas, schwannomas and MPNSTs) - NF1, NF2 and SMARCB1." (PMID 24009526, 2013). "Neurofibromas are benign nerve sheath tumors and the hallmark lesion of the NF1." (PMID 23049566, 2012). "Two types of congenital NF1 mutations have been found to influence neurofibroma number." (PMID 22550514, 2012). "Inactivation of both NF1 alleles as well as loss of heterozygosity (LOH) of microsatellite DNA within the NF1 gene could also be demonstrated in benign NF1-associated neurofibroma." (PMID 16961930, 2006). "However, specific features of NF1, such as neurofibromas within the airways, could predispose individuals to OSA." (PMID 40299482, 2025). "Interestingly, analysis of Nf1-deficient SCs demonstrated that although neurofibromas could originate from adult SCs, the nerve environment could switch from tumor-suppressive to tumor-promoting at a site of injury." (PMID 40940747, 2025).
neurofibroma (continued). "Among other features, the NF1 microdeletion phenotype is associated with somatic overgrowth, dysmorphic features (notable in adolescence and adulthood), more severe cognitive challenges, the earlier appearance with greater numbers of neurofibromas, and an increased risk of developing MPNST." (PMID 38596211, 2024). "We have previously shown that selumetinib, an MEK inhibitor recently approved for treatment of NF1-associated neurofibromas, reaches higher concentrations in the brain of NF1 minipigs compared with WT minipigs, which may be due to alterations in the blood-brain barrier." (PMID 37520682, 2023). "Thus, NF1 is considered a RASopathy and drugs targeting the RAS/mitogen-activated protein kinase (MAPK) pathway, such as the MAP kinase (MEK) 1/2 inhibitor Selumetinib, are promising therapeutic options to treat NF1-associated tumors, especially plexiform neurofibromas and optic way gliomas." (PMID 36923276, 2023). "However, no conclusion could be drawn as to which stage in the SC lineage was critical for neurofibroma formation mediated by NF1 loss." (PMID 36139671, 2022). "Nevertheless, interestingly, previous studies showed that NF1-associated neurofibromas present neoplastic Schwann cells with lipid droplets accumulation, express leptin and have higher chances of having intermingled adipocytes than non NF1-associated neurofibromas." (PMID 36064430, 2022). "However, multiple neurofibromas are the pathognomonic hallmark of NF1." (PMID 33659131, 2021). "We examined the expression of p-STAT3 and Ref-1 in mice that have conditional ablation Nf1 and Arf in neural crest-derived Schwann cells that spontaneously develop a full spectrum of NF1-associated nerve sheath tumours including plexiform and atypical neurofibroma as well as MPNST." (PMID 33658640, 2021). "However, given the extraordinarily high prevalence of Ras pathway activation in human tumors, including Schwann cell-derived tumors, e.g., neurofibromas caused by loss of NF1, regulation of Ras signaling very likely contributes significantly to merlin’s tumor suppressor activity." (PMID 31312020, 2019). "Both benign neurofibromas (Schwann cell tumors) and MPNSTs (also Schwann lineage) are thought to follow the two-hit mechanism, where the initiating tumor cell has most commonly lost the other NF1 allele by somatic mutation, rendering the cell deficient in neurofibromin activity." (PMID 29854299, 2018). "NF1 is commonly associated with higher incidence in many kinds of benign or malignant tumors, such as optic pathway glioma, chronic myeloid leukemia, or pheochromocytoma, neurofibroma, and MPNST, and is related to mutations in NF1 gene located in chromosome 17q11.2." (PMID 24971186, 2014). "Several forms have been described: cutaneous neurofibromas (both localised and diffuse types), intraneural neurofibromas (localised and plexiform), massive soft tissue neurofibromas (solitary or multiple), and sporadic neurofibromas or those associated with neurofibromatosis-1 (NF-1)." (PMID 23653673, 2013). "Likewise a mild NF1 variant associated with a 3-basepair inframe deletion of exon 17 (c.2970-2972 delAAT) has been described in which neurofibromas are rare and multiple CALM may be the only apparent manifestation." (PMID 21089071, 2011). "It is thought that neurofibromas arise when a NF1 two-hit SC begins proliferating in response to wound-like environment signals (even without an actual wound), regardless of contact with an axon, and stimulates production of stroma as well." (PMID 41564118, 2026). "We also investigated the possible relevance of the presence of CALMs in relation to key prognostic factors of disease outcome, such as the likelihood of neurofibroma development, including plexiform neurofibromas, and other NF1-related complications." (PMID 40361417, 2025).
neurofibroma (continued). "We explored the Prss56-Nf1 knockout (KO) mouse model that recapitulates neurofibromas and pseudarthrosis by carrying Nf1 gene inactivation in Prss56-expressing boundary cap cells, a neural crest subset, and their derivatives." (PMID 41397954, 2025). "Clinically, these cases combine intestinal inflammation from UC (e.g., bloody diarrhea, abdominal pain) with classic NF1 features (café-au-lait spots, neurofibromas, skeletal abnormalities)." (PMID 41346988, 2025). "Bi-allelic inactivation in the NF1 gene is the initiating event in neurofibroma formation and a crucial precursor to malignancy, especially in NF1-associated MPNSTs." (PMID 41463204, 2025). "Low-grade MPNSTs (approximately 10% of all MPNSTs) typically arise from NF1-related neurofibromas and can be distinguished from ANNUBP primarily based on mitotic activity, necessitating caution in diagnosis." (PMID 40308487, 2025). "The distinction between HNS, Nf and Sw remains challenging and can result in the misdiagnosis of a neurofibroma suggesting NF1 instead of SWN." (PMID 41247561, 2025). "These tumors are rare in the general population; however, they are enriched among patients with NF1 who show malignant transformation of previously benign neurofibromas." (PMID 40563647, 2025). "Neurofibromas and bone lesions are age-dependent disease complications that exhibit progressive tendencies with increasing age in patients with NF1." (PMID 40410838, 2025). "The proband was previously thought to have NF1 for her early onset and rapid increase of neurofibromas." (PMID 40046620, 2025). "We built a single-cell dataset of 55 NF1-associated PN, AN, and MPNST to define cellular changes in neurofibroma at-risk of malignant transformation." (PMID 40585258, 2025). "The NF-related cases included both NF1- and NF2-associated tumors, encompassing optic pathway gliomas, low-grade gliomas, neurofibromas, and schwannomas." (PMID 40313757, 2025). "Benign peripheral nerve tumors known as neurofibromas arise because of biallelic inactivation of the tumor suppressor gene Neurofibromatosis type 1 (NF1) in nerve Schwann cells." (PMID 40992926, 2025). "Initial biopsy suggested neurofibroma, confirmed by whole‐exome sequencing revealing a 17q11.2 microdeletion involving the NF1 gene." (PMID 40225101, 2025). "In this context, pharmacological inhibition of neuronal excitability using tetrodotoxin significantly reduces neurofibroma growth in NF1-mutant mouse models in vivo." (PMID 41163091, 2025). "These include multiple café-au-lait macules, neurofibromas, axillary or inguinal freckling, optic gliomas, Lisch nodules, osseous lesions, or a first-degree relative with NF1." (PMID 41487738, 2025). "Neurofibromatosis Type 1 (NF-1): This is a monogenic disorder with autosomal dominant inheritance, characterized by cutaneous neurofibromas, café-au-lait spots, and other dermatological manifestations." (PMID 40141713, 2025). "The schwannoma–neurofibroma hybrid is one of the more commonly described HPNST variants and is frequently associated with NF1- and NF2-related schwannomatosis, as well as other forms of schwannomatosis." (PMID 40218204, 2025). "The patient’s symptoms of rapid growth and new-onset pain are classic warning signs for potential malignant transformation or the development of an atypical lesion within a pre-existing neurofibroma in the context of NF1." (PMID 40700245, 2025). "In relation to this, DNA methylation profiling was performed on 29 tumour samples and adjacent neurofibroma tissue from 13 patients with MPNSTs as well as NF1-MPNST cell lines in order to identify CpG sites specific to malignant transformation." (PMID 40843672, 2025). "The significant variability in clinical presentation, unpredictable progression of NF-1, and uncertain growth rates of plexiform neurofibromas contributed to an unclear overall medical prognosis for this patient." (PMID 40230769, 2025).
neurofibroma (continued). "There are cutaneous stigmata of NF-1 in the form of multiple café-au-lait macules on the chest, abdomen, and back, along with a few small cutaneous neurofibromas over the abdomen." (PMID 41185817, 2025). "Several other MEK inhibitors (binimetinib, mirdametinib, trametinib) and the tyrosine kinase inhibitor cabozantinib are also being investigated as medical therapies for NF1-related plexiform neurofibromas." (PMID 39857730, 2025). "RAS/MAPK pathway alterations serve as the driver in the majority of pLGGs, a subset of pHGG and NF1-related plexiform neurofibromas (PNs)." (PMID 40422539, 2025). "Tier IA predictors were identified in two cases of melanoma and low-grade spindle-cell sarcoma (BRAF p.V600E, three patients) and plexiform neurofibroma (NF1 aberrations, two patients)." (PMID 41373618, 2025). "We present the case of a four-year-old girl with NF1 who developed a unique clustering of optic nerve glioma, plexiform neurofibroma, and secondary glaucoma, underscoring the spectrum and severity of ocular involvement in this condition." (PMID 41341331, 2025). "The clinical development of selumetinib for NF1-related plexiform neurofibromas represents a landmark achievement in targeted therapy for rare diseases." (PMID 40725763, 2025). "Another Tier IA predictor, tumor-specific NF1 aberration, warranted TT with selumetinib in a patient with unresectable plexiform neurofibroma, resulting in disease stabilization." (PMID 41373618, 2025). "Neurofibromatosis type 1 (NF-1) is an autosomal-dominant disorder characterized by café-au-lait spots, cutaneous and plexiform neurofibromas, and a spectrum of vascular abnormalities." (PMID 40922847, 2025). "Plexiform neurofibromas are found in the regions of the head, neck, face, and larynx in approximately 50% of cases of NF-1." (PMID 40230769, 2025). "We studied a group of 90 patients with NF1-related plexiform neurofibromas (PNs) with an average age of 15.7 years and a follow-up period of 9.8 yrs." (PMID 39796750, 2025). "Plexiform neurofibroma cell line ipNF95.11bC is significantly more sensitive to AgNP compared to NF1-patient-matched control ipnNF95.11C Schwann cells." (PMID 38543265, 2024). "We conclude that although rare, NPcis mice can develop neurofibroma in a peripheral nerve, which is common in NF1 patients but rare in Nf1 tissue-specific knockout mouse models of neurofibroma." (PMID 38900740, 2024). "NF-1 is an autosomal dominant inherited disorder characterized by café-au-lait spots and neurofibromas, with vascular lesions reported in only 0.4%-6.4% of affected patients." (PMID 39726461, 2024). "As Schwann cells are critical to the NF1 phenotype and formation of neurofibromas, we further assessed DGE data specifically in Schwann cells." (PMID 38907342, 2024). "In the past two decades, tissue-specific Nf1 knockout mouse models were developed using commercially available tissue-specific Cre recombinase and the Nf1 flox mice to mimic neurofibroma development." (PMID 38900740, 2024). "Studies using a tamoxifen-inducible Cre recombinase, driven by the P0 promoter to disrupt Nf1 in mSCs, showed that Nf1-/- repair mSCs promote neurofibroma formation at the injured nerve." (PMID 38473354, 2024). "Neurofibroma, as a component of NF-1, is an autosomal dominant genetically inherited disease that causes multiple tumors." (PMID 38909194, 2024). "Consistently, SUZ12 is highly expressed during early stage of heart development and its LoF is associated to MPNSTs and in general the early onset of several neurofibromas in NF1 microdeletion patients." (PMID 38874808, 2024).
neurofibroma (continued). "It took about a decade from the time the NF1 gene was first cloned to develop the first mouse model recapitulating neurofibroma and MPNSTs." (PMID 38900740, 2024). "Plexiform neurofibroma cells (ipNF95.11bC) and NF1-patient matched Schwann cells were treated with AgNP ranging from 0–500 μg mL−1 (by Ag content) for 72 h." (PMID 38543265, 2024). "In this regard, prior work focused on peripheral nervous system tumors in NF1 (neurofibromas) have shown that neurofibromas develop specifically at wound sites in mice with embryonic Nf1 loss in Schwann cell progenitors." (PMID 38308315, 2024). "The presence of café-au-lait spots on the body and limbs, multiple neurofibromas over the trunk and face, her NF1 gene mutation, and family history of NF-1 in a first-degree relative (sister) confirmed the diagnosis of NF-1." (PMID 39403336, 2024). "The MEK inhibitor selumetinib is an effective treatment for neurofibromas in patients with NF-1 but shows mixed results for MPNSTs11–13." (PMID 38216572, 2024). "The cardinal features of NF1 are due to NF1 inactivation in melanocytes (e.g. café-au-lait macules, iris hamartomas) or Schwann cells (neurofibromas)." (PMID 38900740, 2024). "NF1 plexiform neurofibroma (pNF1) is a complex tumor composed of Schwann cell-derived tumor cells (Nf1−/−) and the tumor microenvironment (TME)." (PMID 39061138, 2024). "We have recently observed a similar mutation (p.Val777Leu) in a case of multiple hybrid schwannoma-neurofibromas unassociated with clinically recognizable NF1 or NF2 syndrome (Agaimy, unpublished data)." (PMID 39196362, 2024). "To determine if PRC2 inactivation was sufficient for selumetinib resistance, we used CRISPR interference (CRISPRi) to suppress SUZ12 or EED in NF1-mutant NF95.11b neurofibroma cells." (PMID 38216572, 2024). "While none of our patients suffered from a known NF2, 4/33 patients (12,1%) had a known NF1: in the case of 2 neurofibromas and 2 MPNSTs." (PMID 39434082, 2024). "Except for cutaneous neurofibromas, which are encountered in almost all patients affected by NF1 (99%), subcutaneous or deep neurofibromas are reported to be found in about 15% of patients." (PMID 38893021, 2024). "Café-au-lait macules (CALMs) are the most frequent and innocuous disease manifestations of NF1, followed by axillary freckling, neurofibromas, and Lisch nodules along with NF1-specific disease complications." (PMID 39257551, 2024). "In this patient, the NF1 diagnosis arose based on the presence of mandibular neurofibromas and café-au-lait macules on the skin." (PMID 38755192, 2024). "In this study, we use NF1-patient matched cell lines derived from both plexiform neurofibroma and adjacent Schwann cells." (PMID 38543265, 2024). "Neurofibromatosis type 1 (NF-1) is an autosomal dominant inherited disorder primarily characterized by café-au-lait spots and neurofibromas." (PMID 39726461, 2024). "In the field of NF1 research, studies evaluating collagen in NF1-mediated tumorigenesis have only been conducted in the context of skin wound healing and neurofibromas." (PMID 38799507, 2024). "NF-1 is fully penetrant, and it is commonly manifested by café-au-lait macules, axillary and/or inguinal freckling, neurofibromas, and Lisch nodules in the eyes." (PMID 38380111, 2024). "Nf1-/- SCs overexpress pleiotropin and midkine, homologous ligands that bind to receptor tyrosine kinases, serve as potent mitogens for neurofibroma derived cells, and are known to increase in response to inflammation and NF-κB-dependent signaling." (PMID 38473354, 2024). "CDKN2A/p16 inactivation is a well-recognized key event in the malignant transformation of neurofibromas in NF1." (PMID 38178234, 2024). "Other MEK inhibitors (binimetinib, mirdametinib, and trametinib) are also currently being investigated for NF1 plexiform neurofibromas." (PMID 38541874, 2024).